PLIN1 (perilipin 1)
Diseases named in the same sentence as PLIN1 in open-access papers (continued):
Sharing a sentence is not in itself a finding about the gene and the disease.
lipodystrophy (continued). "Haploinsufficiency was originally proposed as a mechanism explaining the autosomal dominant phenotype of PLIN1-related lipodystrophy." (PMID 35235652, 2022). "For in vivo study, Plin1-/- mice at 8 weeks old already showed typical histologic phenotype of lipodystrophy featured by insufficient unilocular adipocytes and aberrant adipocyte morphology." (PMID 25695774, 2015). "At least ten lipodystrophy-associated genes have been identified, including phosphate acetyltransferase (AGPAT2), phosphoinositide-dependent serine-threonine protein kinase (AKT2), seipin (BSCL2), caveolin 1 (CAV1) and perilipin 1 (PLIN1)." (PMID 38454882, 2024). "Our large genotype-first approach study suggests that haploinsufficiency of PLIN1 causes a favorable metabolic profile rather than the adverse metabolic profile of lipodystrophy." (PMID 35235652, 2022). "This means that novel PTVs of PLIN1 should not be reported back to patients as a cause of their lipodystrophy." (PMID 35235652, 2022). "Examination of the raw images of BSCL2/PLIN1 ablated cells revealed cells with decreased lipid accumulation overall, but with strikingly large residual lipid droplets as compared to control cells or cells ablated for other lipodystrophy genes such as PPARG." (PMID 30940487, 2019). "We present six probands and five family members who have null variants in PLIN1 but no phenotype of lipodystrophy." (PMID 30020498, 2018). "The lack of an overt lipodystrophy phenotype in patients with null variants in PLIN1 raised questions over the pathogenicity of protein truncating variants in this gene." (PMID 30020498, 2018). "Our study suggests that heterozygous null variants in PLIN1 do not cause overt lipodystrophy and provides another example of a gene where only variants with specific genetic mechanisms cause lipodystrophy." (PMID 30020498, 2018). "We investigated sequencing data from over 140,000 people and established that null variants in PLIN1 do not cause lipodystrophy." (PMID 30020498, 2018). "In addition to one previously reported case in FPLD1, RYGB has been used in FPLD2 (LMNA) and FPLD4 [perlipin 1 (PLIN1)] monogenic lipodystrophies." (PMID 28973478, 2017). "Here we show that, rather than causing a lipodystrophy phenotype, PLIN1 haploinsufficiency causes a favorable metabolic profile and may protect against cardiovascular disease." (PMID 35235652, 2022). "We suggest that novel PTVs in PLIN1 should not be reported as a cause of lipodystrophy." (PMID 35235652, 2022). "However, we studied 6 individuals with protein-truncating variants (PTVs) of PLIN1 who lacked features of lipodystrophy and had normal lipid profiles." (PMID 35235652, 2022). "The pathogenicity of other PLIN1 null variants identified in patients with diabetes and/or hyperinsulinemia was recently questioned because of the absence of lipodystrophy in these individuals and the elevated frequency of PLIN1 null variants in the general population." (PMID 31504636, 2019). "We recommend that null variants in PLIN1 should not be reported as causative of lipodystrophy." (PMID 30020498, 2018). "This discrepancy may be attributed to recent doubts about the pathogenicity of other PLIN1 variants found in patients with diabetes, stemming from the absence of lipodystrophy in these individuals and the higher prevalence of PLIN1 variants in the general population." (PMID 41614819, 2025). "For two lipodystrophy genes, BSCL2 and AGPAT2, sub-clusters with PLIN1 and CEBPA identifed by morphological similarity were validated by independent experiments as novel protein–protein and gene regulatory interactions." (PMID 30940487, 2019). "First, we were not able to search for another mutations linked to lipodystrophy phenotypes (PPARG, AKT2, and PLIN1)." (PMID 22938045, 2012). "Following this approach, we identified anti-perilipin 1 IgG autoantibodies in the serum of patients with autoimmune variety-AGL, but in no other lipodystrophies tested." (PMID 30283460, 2018).
Insulin resistance (22 papers, 2013 to 2026). Increased resistance towards insulin, that is, diminished effectiveness of insulin in reducing blood glucose levels. "For example, people carrying frameshift mutations on PLIN1 (coding for perilipin-1, the most abundant lipid droplet coat protein in adipocytes) show partial lipodystrophy, severe insulin resistance, and T2D." (PMID 38967989, 2024). "Loss-of-function mutations in PLIN1 have been reported to lead to familial partial lipodystrophy, severe insulin resistance, and diabetes." (PMID 31086609, 2019). "Three heterozygous protein extending frameshift variants in PLIN1 have been reported to cause a phenotype of partial lipodystrophy and insulin resistance." (PMID 30020498, 2018). "Heterozygous protein extending frameshift variants in PLIN1 have been reported to cause a phenotype of partial lipodystrophy and insulin resistance." (PMID 30020498, 2018). "Levels of Plin1 were also examined since recent reports have implicated a potential role for Plin1 in the development of insulin resistance." (PMID 24040030, 2013). "Our previous studies identified PLIN1 variants that interact with the saturated fatty acid-to-carbohydrate ratio to influence insulin resistance." (PMID 24204828, 2013). "Together, these data suggested that Plin1 protein enhances catecholamine-stimulated lipolysis and, importantly, that a reduction in Plin1 protein expression is associated with increased constitutive lipolysis, which can promote systemic insulin resistance." (PMID 25132820, 2014). "In mice, the depletion of perilipin 1 (PLIN1) results in a lean phenotype, accompanied by insulin resistance and glucose intolerance." (PMID 39139927, 2024). "Deram and colleagues identified two different patterns that link pediatric obesity, insulin resistance, and lipid metabolism for the perilipin 1 gene (PLIN1; OMIM * 170290) variations in children and adolescents." (PMID 36986146, 2023). "In summary, PLIN1 gene SNP rs6496589 has a substantial role in metabolic disorders, insulin resistance, and the development of T2DM." (PMID 35886029, 2022). "It is known to mediate lipolysis and insulin resistance by downregulation of PLIN1 and CIDEA expression." (PMID 27900559, 2017). "In mice, perilipin 1 dysfunction leads to a leanness phenotype, exhibiting glucose intolerance and insulin resistance, whereas the complete lack of perilipin 1 on the background of a mutation in the leptin receptor gene inhibits obesity." (PMID 35277579, 2022). "In addition, Plin1 deficiency reveals partial fat loss, ATM accumulation, dyslipidemia and systemic insulin resistance in both mouse and human." (PMID 33584664, 2020). "Plin1-null mice are lean and develop systemic insulin resistance as they grow older." (PMID 25132820, 2014). "Also, when lipid storage capacity of adipocytes is defective by ablation of lipid droplet (LD) binding proteins such as Perilipin1 (Plin1), the levels of triglyceride and FFAs are elevated in adipose tissue and serum, which is accompanied by adipose tissue inflammation and insulin resistance." (PMID 33584664, 2020). "Among the 10 most upregulated genes in NAFLD were genes related to insulin resistance (PRKCE), glucose metabolism and steatosis (PLIN1), glucose uptake regulation (ISM1), oxidative cell stress response (TP53INP1), and a proinflammatory marker (SERPINE 1)." (PMID 40489530, 2025).
diabetes (13 papers, 2014 to 2025). "Frameshift mutations in the PLIN1 gene, encoding perilipin 1 (a lipid droplet surface protein that regulates lipolysis), result in autosomal dominant partial lipodystrophy associated with severe dyslipidemia and diabetes." (PMID 38706718, 2024). "In patients with insulin requiring type 2 diabetes mellitus, perilipin 1 mRNA and protein levels were reduced when the insulin was withheld and patients were hyperglycemic compared to when they were on insulin and euglycemic." (PMID 25118138, 2014).
familial partial lipodystrophy (10 papers, 2018 to 2025). "The prevalence of familial partial lipodystrophy would need to be greater than 1 in 10,000 to be consistent with null variants in PLIN1 causing the disorder." (PMID 30020498, 2018). "Genetic variants in PLIN1 causes familial partial lipodystrophy (FPLD), type 4." (PMID 35207755, 2022). "The association between RIP3, perilipins (PLIN1 and PLIN5), and disease severity has been demonstrated in patients with MASLD and familial partial lipodystrophy." (PMID 38195700, 2024). "Regarding Familial Partial Lipodystrophy (FPLD), the main subgroups, FPLD2 to 6, are associated with pathogenic variants in LMNA, PPARG, PLIN1, CIDEC and LIPE respectively, whereas FPLD1 is thought to be of polygenic origin." (PMID 38678257, 2024). "Our study suggests that heterozygous variants that are predicted to result in PLIN1 haploinsufficiency are not a cause of familial partial lipodystrophy and should not be reported as disease-causing variants by diagnostic genetic testing laboratories." (PMID 30020498, 2018). "However, another study suggested that heterozygous variants in the PLIN1 gene do not cause familial partial lipodystrophy and should not be classified as disease-causing." (PMID 41614819, 2025). "Partial lipodystrophy syndromes are classified into Familial Partial Lipodystrophy (FPLD) including FPLD1 (Köbberling syndrome), FPLD2 (Dunnigan syndrome, due to mutations in the LMNA gene), FPLD3 (PPARG gene), FPLD4 (PLIN1 gene), FPLD5 (CIDEC gene), FPLD6 (LIPE gene) gene mutations." (PMID 41341138, 2025).
Hepatic steatosis (9 papers, 2016 to 2025). Steatosis is a term used to denote lipid accumulation within hepatocytes. "Perilipin1 (PLIN1) was found to be involved in the pathogenesis of hepatic steatosis and is a modulator of adipocyte lipid metabolism with related pathways in glucose and energy metabolism." (PMID 40489530, 2025). "Both the Lsd and Perilipin proteins are known for their physiological roles in modulating lipid content; for example, the Plin1-null mice are lean while the down-modulation of Plin2 alleviates hepatic steatosis." (PMID 31725726, 2019). "Treatment with the clinical candidate, obeticholic acid reversed the hepatic steatosis phenotype and transcriptomic analysis confirmed the selective activation of FXR target genes including upregulation of FGF19 and PLIN1 and downregulation of SLC51B and CYP7A1 genes by OCA." (PMID 33334026, 2020).
dyslipidemia (8 papers, 2016 to 2025). "The published patients with pathogenic PLIN1 variants had dyslipidemia with hypertriglyceridemia (range from 2 to 147 mmol/L); all of the patients in our study with variants in PLIN1 had triglyceride levels below 1.7 mmol/L." (PMID 30020498, 2018). "Regular physical exercise triggers lipolytic effects in adipose tissue through cGMP, HSL, and perilipin-1-mediated pathway in fructose-induced metabolic syndrome model in rats, preventing the increase in adipocyte diameter." (PMID 39954126, 2025).
partial lipodystrophy (8 papers, 2015 to 2024). Loss and redistribution of subcutaneous and/or visceral adipose tissue from specific regions of the body. "PLIN1 null variants occur too frequently in gnomAD (126/138,632; 1 in 1100) to be a cause of rare overt monogenic partial lipodystrophy." (PMID 30020498, 2018). "Our finding suggests that Plin1 plays an important role in adipocyte differentiation and provides an insight into the pathology of partial lipodystrophy in patients with Plin1 mutation." (PMID 25695774, 2015). "Interestingly, several heterozygous PLIN1 frameshift variants had previously been linked to partial lipodystrophy." (PMID 34875679, 2022). "We show that the phenotype of individuals with PLIN1 haploinsufficiency is inconsistent with the presence of clinical partial lipodystrophy (low HDL, high triglycerides, adverse metabolic disease)." (PMID 35235652, 2022). "Mutations in lamin A/C, peroxisome proliferator-activated receptor-γ (PPARγ), fat-specific protein 27-kDa (Fsp27/Cidec) and perilipin 1 (Plin1) lead to partial lipodystrophy." (PMID 25695774, 2015). "In contrast, adipose tissues in Plin1-/- mice at 8 weeks old already showed typical histologic characteristics of partial lipodystrophy, as indicated by plenty of small unilocular adipocytes, with multiple small lipid droplets in cytoplasm." (PMID 25695774, 2015). "Our finding may provide a mechanic explanation for the pathology of partial lipodystrophy in patients with Plin1 defect." (PMID 25695774, 2015). "Plin1 defect leads to low adiposity in mice and partial lipodystrophy in human." (PMID 25695774, 2015).
atherosclerosis (6 papers, 2011 to 2025). A disease characterized by the build-up of fatty material and calcium deposition in the arterial wall resulting in partial or complete occlusion of the arterial lumen. "The atherosclerosis decrease was also associated with a macrophage polarity change in plaque, following the high expression levels of Plin1." (PMID 39859272, 2025). "The role of Plin1 in foam cells is significant in the accumulation of lipids in the arterial wall, thus influencing atherosclerosis development." (PMID 39859272, 2025). "The main aim of collecting the data was to clarify the role of PLIN1 in the pathophysiology of atherosclerosis." (PMID 29892631, 2018). "Accumulated evidence have indicated the role of Plin1 in atherosclerosis, however, these findings are controversial." (PMID 25855981, 2015).
Hypertension (6 papers, 2017 to 2023). The presence of chronic increased pressure in the systemic arterial system. "The present study demonstrated that lipolysis activities and FFA β-oxidation were increased in rats with hypertension-induced HF, as characterized by the upregulation of HSL and perilipin-1 as well as the rate-limiting enzyme CPT-1." (PMID 36670439, 2023).
type 2 diabetes (6 papers, 2014 to 2022). "It would be interesting to determine the functional consequences of PLIN1 null variants identified in the general population or in those with maturity onset diabetes of the young." (PMID 31504636, 2019). "We also investigated the frequency of PLIN1 variants in the gnomAD database, and the type 2 diabetes knowledge portal." (PMID 30020498, 2018).
steatosis (5 papers, 2017 to 2025). Increased lipid within the cytoplasm of cells. "However, in the later stages of NAFL, the size of LDs increases considerably, and PLIN2 is replaced by PLIN1, a hallmark of LD maturation and macrovesicular steatosis." (PMID 37958873, 2023). "We also looked at the mRNA expression of apolipoprotein A4 (APOA4) and perilipin 1 (PLIN1) because these lipid-related genes are consistently overexpressed whenever steatosis occurs, including in the context of NAFLD." (PMID 30147834, 2018). "The liver Plin1 via qPCR was 9-fold higher in SEIPIN KO than WT (p=0.04), consistent with probable steatosis, which was also supported by gross examination demonstrating enlarged, pale livers." (PMID 35145475, 2021). "KO weighed 14% less than WT (p=0.01) and exhibited an absence of epididymal adipose tissue; KO liver Plin1 via qPCR was 9-fold that of WT (p=0.04), consistent with steatosis." (PMID 35145475, 2021).
cardiac hypertrophy (3 papers, 2020 to 2025). "Similarly, Plin isoforms show differential regulation under physiological and pathological conditions, such as during pregnancy-induced cardiac hypertrophy in rats, where increased expression of Plin1, Plin2, and Plin5 is observed." (PMID 39859272, 2025). "In addition, Plin1−/− mice showed cardiac hypertrophy, leading to heart failure with left ventricular diastolic dysfunction at 20 weeks of age." (PMID 39859272, 2025). "Downregulation of PLIN1 in mice led to excessive cardiac hypertrophy and failure." (PMID 32831121, 2020).
generalized lipodystrophy (3 papers, 2018 to 2025). Almost complete absence of subcutaneous and/or visceral adipose tissue. "Our data provide strong support for the conclusion that perilipin 1 autoantibodies are a cause of generalized lipodystrophy in these patients." (PMID 30283460, 2018). "Our data provide strong support for the conclusion that anti-PLIN1 autoantibodies are implicated in the pathogenesis of the generalized lipodystrophy in these patients." (PMID 30283460, 2018).